TNF (tumor necrosis factor)
Diseases named in the same sentence as TNF in open-access papers (continued):
Sharing a sentence is not in itself a finding about the gene and the disease.
orchitis (14 papers, 2015 to 2026). Inflammation of one or both testes due to viral or bacterial infections. "Fibrosis, caspase-3 expression, and accumulations of tumor necrosis factor-α (TNF-α; P < 0.05) and interleukin-1β (IL-1β; P < 0.05), along with an elevated macrophage composition (P < 0.05) characterized the orchitis under HS." (PMID 41402910, 2025). "Animals subjected to LPS were found to have severe orchitis, as evidenced by increased oxidative stress and surging inflammatory mediators (TNF-α, IL-1β, and IL-6), with declined IL-10 levels." (PMID 39845795, 2024). "In this study, the mRNA expressions of IL-2, TNF-α, IL-17A, and IL-1β, which have essential roles in inflammatory processes, were elevated in LPS-induced orchitis; however, PHN have been found to reduce their expression." (PMID 38846786, 2024). "Considering that IL1α and TNFα are highly produced in orchitis, the possible role of these cytokines in Sertoli cell proliferation under inflammatory conditions is feasible." (PMID 38666890, 2024). "Many studies have also shown that an imbalance between pro- and anti-inflammatory molecules, including TNF-α and IL-1β, in the testes can lead to orchitis." (PMID 38846786, 2024). "IMD can inhibit the gene expression of the proinflammatory cytokines (TNF-α, IL-6, and IL-1β) in LPS-induced rat testis inflammation." (PMID 34434487, 2021). "The orchitis-related testicular impairment could be exerted on Leydig cells, and TNF-α could serve as a histone deacetylase 7 activator." (PMID 41402910, 2025). "Lipopolysaccharides (LPS) is a key element of the external membrane found in Gram-negative bacteria and can cause orchitis by promoting the production of ROS and inflammatory mediators such as TNF-α, IL-6, and IL-1β in testicular tissue." (PMID 39845795, 2024). "Orchitis may be induced by discrepancies in the inflammatory and anti-inflammatory cytokine levels in testicular cells, including TNF-α, interleukin (IL)-1β, (IL-6), and IL-10." (PMID 39845795, 2024). "In addition, exosomes isolated using a mouse model of UPEC-induced orchitis promoted macrophage M1 activation and consequently increased the levels of proinflammatory cytokines (e.g., TNFα, IL-1β, and IL-6) in the testes." (PMID 38190378, 2024). "In orchitis, the overexpression of IFN-γ and TNF-α and the synergy between these cytokines impair spermatogenesis." (PMID 41596343, 2026). "MuV-induced orchitis suppresses testosterone synthesis, induces germ cell apoptosis, and impairs BTB integrity, in which high levels of tumor necrosis factor-alpha (TNF-α) play a crucial role." (PMID 40607213, 2025). "Increasing evidences indicate that the imbalance among these pro- and anti-inflammatory molecules, such as interleukin-1β (IL-1β), IL-6, tumor necrosis factor-α (TNF-α), and IL-10, in testicular cells can result in orchitis." (PMID 32922653, 2020). "In a rat model of testis inflammation, ADM2 treatment protected against LPS-induced damage by decreasing the levels of reactive oxygen species, TNF-α, IL-6, and IL-1 ß." (PMID 26485688, 2015).
pancreatic adenocarcinoma (14 papers, 2003 to 2025). "The IL-8 concentration also seemed to be associated with or influenced by IL-6 and TNFα levels in patients with pancreatic adenocarcinoma." (PMID 24849506, 2014). "In pancreatic adenocarcinoma cells, 1,25-(OH)2D3 ameliorates the pro-invasive action of tumor necrosis factor (TNF)-α by decreasing the expression of miR-221 and increasing that of the tissue inhibitor of metalloproteinase (TIMP)-3." (PMID 35406059, 2022). "They provide a rational for the combination of TNFα, BAb, and RT in the treatment of adenocarcinoma of the pancreas." (PMID 14612914, 2003). "In addition, patients with pancreatic adenocarcinoma had G-CSF levels that were similar to healthy individuals, and significantly higher TNFα concentrations." (PMID 24849506, 2014). "Our analysis demonstrated that IL-6, IL-8, IL-10, and TNFα are promising novel candidate markers for the detection of pancreatic adenocarcinoma, whereas IL-23 might be valuable for its ability to exclude a diagnosis of cancer." (PMID 24849506, 2014). "Importantly, patients with pancreatic adenocarcinoma had significantly higher systemic IL-8 and TNFα levels than did individuals diagnosed with other pancreatic malignancies." (PMID 24849506, 2014). "Their activation by different factors, including, for example, IL-1, IL-6, TNF-α, TGF-β1, and activin 1, induces fibrosis and accounts for the desmoplastic property of pancreatic adenocarcinomas." (PMID 38891809, 2024). "Two CAR-T cells showed increased release of IFNγ, TNFα, IL-2 and very limited production of IL-6 after stimulated by four EpCAM positive pancreatic adenocarcinoma cells while not by hTERT–HPNE." (PMID 41417221, 2025). "In pancreatic adenocarcinoma (PDAC), tumorigenesis is promoted by suppression of the function of DCs by exosomes carrying miR-203, which downregulates Toll-like receptor 4 (TLR4), tumor necrosis factor-α (TNF-α), and IL-12 expression, and ultimately prevents antigen presentation by DCs." (PMID 33586060, 2021).
pericardial effusion (14 papers, 2012 to 2025). Fluid collection within the pericardial sac, usually due to inflammation. "Due to absence of documented infection or other identifiable causes of pericardial effusion and in light of highly elevated antibodies against infliximab, it was felt that an immune reaction to anti-TNFα therapy was responsible." (PMID 27822400, 2016). "Colchicine has also been found to significantly reduce the release of various inflammatory factors, including tumor necrosis factor-α and interleukin-1β, which play important roles in inflammatory diseases such as pericardial effusion." (PMID 40988201, 2025). "Hemorrhagic pericardial effusion with cardiac tamponade has previously been described in a single case report in a patient with RA receiving the anti-TNFα agent adalimumab." (PMID 27822400, 2016). "Here, we present a rare case of hemorrhagic pericardial effusion induced by infliximab and review all reported cases of pericardial effusion during anti-TNFα therapy." (PMID 27822400, 2016). "Chronic immune activation and a persistent inflammatory state, with increased blood levels of the inflammatory cytokines–TNFα, IL-6, and CRP, associated with a direct cardiac involvement may induce pericardial effusions, with a lower occurrence among patients under antiretroviral therapy." (PMID 36013560, 2022). "As illustrated by our case, clinicians should be aware of both noninfectious elevations in PCT and anti-TNFα-induced pericardial effusion as rare, but life-threatening adverse effects." (PMID 27822400, 2016). "Therefore we measured the concentrations of VEGF, bFGF, IL-1β, and TNF-α in pericardial fluid and serum from patients with inflammatory, nonmalignant pericardial effusion and patients without pericardial disease." (PMID 22577248, 2012).
polymyositis (14 papers, 2014 to 2025). A rare idiopathic inflammatory myopathy characterized by symmetric proximal muscle weakness and elevated muscle enzymes. "There also seems to be elevations of TNF, IL-1 and IL-6 in both DM and polymyositis (PM) patients." (PMID 37681925, 2023). "However, anti-TNF-α therapies led to disappointing results in clinical trials for diseases such as COPD, heart failure, and polymyositis/dermatomyositis." (PMID 36538023, 2023). "However, the efficacy of TNF-α inhibitors in the treatment of polymyositis is uncertain and has only been reported on a case-by-case basis, with no reports on IL-17A inhibitors in the treatment of polymyositis." (PMID 40441209, 2025).
primary biliary cholangitis (14 papers, 2009 to 2025). Primary biliary cholangitis (PBC) is a chronic and slowly progressive cholestatic liver disease of autoimmune etiology characterized by injury of the intrahepatic bile ducts that may eventually lead to liver failure. "Polymorphisms in the TNFα gene, resulting in increased production of this cytokine, have been linked to the development of primary biliary cholangitis (PBC)." (PMID 35095853, 2021). "After phytohaemagglutinin (PHA) stimulation of these liver T cells, the expression of various cytokines was evaluated within the supernatant by enzyme-linked immunosorbent assay (ELISA), and high expression of TNF-α was demonstrated in PSC as compared with primary biliary cholangitis (PBC)." (PMID 31008013, 2019). "For example, a study in patients with primary biliary cirrhosis revealed the increased levels of IL-1β, IL-6, and TNF-α in such patients compared to healthy controls." (PMID 28299346, 2017). "A specific TNF–alpha variant is only associated with an altered risk of primary biliary cirrhosis when there is an AA genotype, not AG or GG, at the − 318 CTLA4 promoter polymorphism." (PMID 32835228, 2020). "It was found that peripheral TNF-α could indirectly cause microglia activation and subsequent recruitment of monocytes into the brain and in situ production of TNF-α through stimulating the activation of cerebrovascular endothelial cells in an animal model of biliary cirrhosis." (PMID 28870240, 2017). "In primary biliary cholangitis (PBC), hepatic expression of SOCS1 is inhibited by microRNA-155, which may result in the increased production of proinflammatory cytokines such as tumor necrosis factor α (TNFα) and interleukin 1β (IL-1β)." (PMID 31717271, 2019).
primary open-angle glaucoma (14 papers, 2008 to 2025). "The purpose of this study was to investigate the clinical factors associated with elevated TNF-α and its level in aqueous humor of patients with open-angle glaucoma (OAG)." (PMID 36079162, 2022). "Further studies are required to elucidate whether the decrease of serum TNF-α concentration in PSS patients is associated with the characteristics of open angle glaucoma in PSS." (PMID 28384257, 2017). "It is unclear whether medications with anti-TNF properties such as bupropion have an impact on the risk of developing open-angle glaucoma (OAG) in humans." (PMID 25875446, 2015). "In a meta-analysis, open-angle glaucoma patients appeared to have higher AH levels of TNF-α than the control group." (PMID 37020269, 2023). "Our previous clinical study showed significantly lower serum TNF-α in primary open-angle glaucoma (POAG) patients than in controls, while the levels of IL-4, IL-6, and IL-12p70 were significantly higher." (PMID 25811482, 2015). "Furthermore, TNF-α levels were elevated in aqueous humor of patients with open-angle glaucoma (OAG) compared to normal subjects in a few studies." (PMID 36079162, 2022).
psychological distress (14 papers, 2020 to 2026). "In conclusion, we found that psychological distress was associated with the cytokines IL-2, IL-4, IL-5, IL-10, IL-12, TNF-α, and IFN-γ." (PMID 36405903, 2022). "However, psychological distress was significantly associated with the plasma cytokines IL-2, IL-4, IL-5, IL-10, IL-12, TNF-α and IFN-γ." (PMID 36405903, 2022). "Pro-inflammatory plasma cytokines, which showed a correlation with higher psychological distress, included interleukin (IL)-2, IL-12, tumor necrosis factor-α (TNF-α), and interferon-gamma (IFN-γ)." (PMID 40151707, 2025). "Salivary TNF-α reflects mucosal and systemic inflammatory states and has been found to be elevated in individuals under chronic psychological distress." (PMID 40728957, 2025). "An encouraging salivary biomarker for emotional dysregulation, elevated TNF-α levels have been regularly seen in those with major depressive disorder (MDD), generalized anxiety disorder (GAD), and persistent psychosocial stress." (PMID 40728957, 2025). "Elevated levels of proinflammatory cytokines, such as interleukin-6 (IL-6) and tumor necrosis factor-alpha (TNF-α), are associated with altered sleep architecture, reduced melatonin production, and increased psychological distress." (PMID 40598531, 2025). "A recent study found that higher psychological distress indirectly predicted worse cognition through higher levels of IL-1β, TNF-α, and IL-4." (PMID 38840166, 2024). "In all mediation models, the A path on behalf of the relationship between psychological distress and cytokine levels (IL‐1β, TNF‐α, and IL‐4) was significant and positive (=4.80, =4.70, =3.25, respectively; <0.05)." (PMID 36965094, 2023). "The indirect effect size of psychological distress on cognitive function through IL‐1β, TNF‐α, and IL‐4 were 26%, 25%, and 24%, respectively." (PMID 36965094, 2023). "Previously, equivocal results dependent upon the stress stimulus under investigation have been reported regarding the effects of psychological distress on serum TNF-α levels." (PMID 33301421, 2021). "Recent research suggested that moderate and high levels of TNF‐α strengthen the relationship between perceived social support and psychological distress, which means that appropriate TNF‐α may be the protective cytokine for psychological distress." (PMID 36965094, 2023). "Psychological distress is common and almost accompanied by the whole process of cancer, and its relationship with cytokines deserved further study though the indirect effect size of psychological distress on cognitive function through IL‐1β, TNF‐α, and IL‐4 is limited." (PMID 36965094, 2023). "However, cytokine levels can be altered by infection and cancer treatment, and an extended follow‐up is required to assess the dynamic course of IL‐1β, TNF‐α, and IL‐4 with psychological distress." (PMID 36965094, 2023). "There are significant changes in the levels of TNF in cells, plasma and serum in patients with AD/MD, which is consistent with abundant evidence that supports the role of inflammation in the development of psychological distress." (PMID 35098831, 2022). "The hypothalamic–pituitary–adrenal axis could synthesize inflammatory mediators (e.g., IL-1, IL-6, and TNF-α) during psychological distress." (PMID 32410849, 2020). "The link between psychological distress and cognitive function as measured by the MMSE was also mediated by IL‐1β, TNF‐α, and IL‐4 (effect size: 26%, 25%, and 24%)." (PMID 36965094, 2023). "Using PROCESS, we investigated whether psychological distress predicted cognitive function based on MMSE through IL‐1β, TNF‐α, and IL‐4." (PMID 36965094, 2023). "The indirect effect of psychological distress via IL‐1β, TNF‐α, and IL‐4 on the MMSE was significant and negative (=−0.34, =−0.32, =−0.32, respectively; 95% CI [−0.59 to −0.17], [−0.52 to −0.16], [−0.54 to −0.13])." (PMID 36965094, 2023).
psychological distress (continued). "However, another study of individuals reporting psychological distress found no significant reduction of IL-6, TNF-α, and CRP post intervention or at follow-up." (PMID 35648793, 2022).
retinal detachment (14 papers, 2009 to 2025). An eye emergency condition which may lead to blindness if left untreated. "After the discontinuation of IFNα2a treated 3 cases who was started anti-TNF-α agents during this period, significantly loss of vision (logMAR ≥2.0) occured in 3 eyes due to the severe former relapses of disease and in one eye rhegmatogenous retinal detachment also happened." (PMID 30290779, 2018). "Studies have shown that TNF-α is an important regulator of photoreceptor autophagy after retinal detachment." (PMID 39114482, 2024). "Both autophagy and retinal inflammation, particularly elevated levels of TNF-α, participate in photoreceptor cell death after retinal detachment." (PMID 36362313, 2022). "Along with MCP-1, induction of TNF-α has also been shown to mediate experimental retinal detachment-induced photoreceptor apoptosis." (PMID 19823583, 2009). "In this study, we examined whether TNF-α inhibition would impact the autophagy of photoreceptors and reduce the death of photoreceptors after retinal detachment (RD)." (PMID 29215050, 2017). "Recently, in C57BL6 mice with N-methyl-N-nitrosourea (MNU)-induced retinal detachment, it was shown that RPE-Exo treatment restores visual function by rescuing photoreceptor cells, significantly lowering TNFα and ILβ mRNA expression and inhibiting apoptosis pathway activation." (PMID 36840007, 2023). "Using Sprague–Dawley rat models with hyaluronic acid-induced retinal detachment and the Rd10 mice model, it was shown that the subretinal injection of MSC-Exos significantly lowers levels of pro-inflammatory cytokines (e.g., TNFα and ILβ) and suppresses photoreceptor cell apoptosis." (PMID 36840007, 2023). "Most cytokines concentrations (IL-2, IL-6, IL-8, IL-10, IL-17, TNF-α, IFN-γ, VEGF) were not statistically significant different compared to the rhegmatogenous retinal detachment control group except IL-1β." (PMID 23049699, 2012). "Macrophage recruitment and expression levels of TNF-a and MCP-1 after retinal detachment were not affected by TUDCA treatment, whereas increases in activity of caspases 3 and 9 as well as carbonyl-protein adducts were almost completely inhibited by TUDCA treatment." (PMID 21961034, 2011).
Takayasu arteritis (14 papers, 2014 to 2023). A rare inflammatory large-vessel vasculitis primarily affecting the aorta and its major branches, but also other large vessels, causing stenosis, occlusion, or aneurysm. "Tumor necrosis factor-α (TNF-α) antagonists are effective against both Blau syndrome and Takayasu arteritis and TNF-α is also a significant inflammatory factor in the NF-κB signaling pathway." (PMID 36915122, 2023). "There is also a report on the serum level of TNF-α elevated in Takayasu’s arteritis, a chronic inflammatory disease with damages in medium and large arteries." (PMID 35464987, 2022). "Several retrospective studies and case series reported that TNF α inhibitors were effective in most patients with refractory Takayasu’s arteritis." (PMID 34209028, 2021). "A two-year follow-up cohort study from Norway reported higher rates of sustained remission as well as lesser progression of angiographic lesions in patients receiving anti-TNF-α agents, when compared with conventional treatments in Takayasu’s arteritis." (PMID 34209028, 2021). "Elevated tumor necrosis factor‐α (TNF‐α) is correlated with refractory Takayasu arteritis (TA), and resistance exercise have been shown to inhibit TNF‐α." (PMID 32761844, 2020). "Some authors have reported favorable results during treatment with biological agents such as anti-TNF agents, the interleukin-6 antibody tocilizumab, and anti-B cell antibodies such as rituximab in patients with Takayasu’s disease." (PMID 28854963, 2017). "Disease activity and inflammation in Takayasu Arteritis (TA) is thought to be mediated through activated monocytes, macrophages and T-cells that synthetize pro-inflammatory cytokines, including TNF-alpha and IL-6." (PMID 27658465, 2016). "Recently there have been reports of large vessels vasculitis (Takayasu's arteritis (TA)) in patients receiving anti-TNF-therapy." (PMID 25544845, 2014). "Therefore, TNF-α is reported to be a therapeutic target of Takayasu’s arteritis." (PMID 35464987, 2022).